IL22 (interleukin 22)
Diseases named in the same sentence as IL22 in open-access papers (continued):
Sharing a sentence is not in itself a finding about the gene and the disease.
gonococcal infection (2 papers, 2018 to 2019). "Conversely, in IL-22-deficient mice, infection was more rapidly eliminated, implying that responses driven by IL-22 signaling promote gonococcal infection in this model." (PMID 31681305, 2019).
HCMV infection (2 papers, 2019 to 2023). "It is thus tempting to speculate that a block in ILC3 development occurring in acute HCMV infection would aggravate the risk of GvHD by selectively depleting IL-22-producing ILC3." (PMID 31861547, 2019). "For the first time, the present study demonstrated the frequency of Th22 cells and production of IL-22 in HCMV infection among kidney transplant patients but with some limitations." (PMID 37403036, 2023). "Overall, this study for the first time suggests that the reduced levels of Th22 subset and IL-22 cytokine in patients with active HCMV infection might indicate the protective role of these cells against HCMV." (PMID 37403036, 2023). "Furthermore, the generation of ILC3, characterized by expression of the signature transcription factor RAR-related orphan receptor gamma (RORγt) and the production of IL-22, was strongly impaired by HCMV infection." (PMID 31861547, 2019). "Here, the frequency changes of Th22 cells and the IL-22 cytokine production were investigated in kidney transplant recipients with and without HCMV infection." (PMID 37403036, 2023). "Therefore, the present study aimed to evaluate the presence and frequency of Th22 cells and their signature cytokine, IL-22, as a first step to shedding light on their functional nature in kidney transplant patients with and without HCMV infection." (PMID 37403036, 2023). "We believe there is no study on the frequency of Th22 cells and IL-22 production in HCMV infection." (PMID 37403036, 2023).
histoplasmosis (2 papers, 2020 to 2023). A disease caused by the fungus Histoplasma capsulatum. "In line with reduced NOS2 expression and NO2− production, we observed that survival of Il22−/− mice during histoplasmosis can be significantly extended by rIFN-γ treatment." (PMID 32517114, 2020). "Due the central role of IL-22 in anti-fungal immunity, we sought to explore its function during experimental histoplasmosis." (PMID 32517114, 2020). "To understand the role of IL-22 during experimental histoplasmosis, we monitored the mortality rate of C57Bl/6 (WT) or Il22−/− mice infected with H. capsulatum for 28 days." (PMID 32517114, 2020). "Despite that, the function of IL-22 during histoplasmosis was largely unknown." (PMID 32517114, 2020). "However, little is known about the role of IL-22 during histoplasmosis." (PMID 32517114, 2020). "Importantly, despite the deleterious role played by the accumulation of neutrophils in several conditions, enhanced neutrophil accumulation in the lung does not seem to be responsible for Il22−/− mice mortality during experimental histoplasmosis." (PMID 32517114, 2020).
HIV-1 infection (2 papers, 2015 to 2021). The type species of lentivirus and the etiologic agent of acquired immunodeficiency syndrome (AIDS). "Selective loss of Th22 cells and a reduction in IL-22 cytokine secretion by CD4 T cells occurred in patients with untreated HIV-1 infection, which was restored in part by ART25." (PMID 26347358, 2015). "A more detailed investigation is necessary to determine whether the presence of circulating Gag-induced IL-22-secreting T cells in EU individuals contributes to the control of HIV-1 infection." (PMID 26347358, 2015).
hypertrophy (2 papers, 2017 to 2018). Hypertrophy is the increase in the volume of an organ or tissue due to the enlargement of its component cells. "H&E staining of heart tissue confirmed that cardiac hypertrophy induced by angiotensin II was prevented by mouse anti-IL-22 nAb." (PMID 29358851, 2017). "The effect of anti-IL-22 on attenuating extracellular fibrosis remodeling is compelling evidence that anti-IL-22 nAb relieves angiotensin II-induced cardiac hypertrophy." (PMID 29358851, 2017). "The first aim of the present study was to examine IL-22/IL-22R1 expression in myocardial hypertrophy." (PMID 29358851, 2017). "Our data demonstrated that neutralization of IL-22 alleviated angiotensin II-induced cardiac hypertrophy." (PMID 29358851, 2017). "Although the effect of IL-1β on angiotensin II-dependent cardiac hypertrophy is unknown, data from clinical settings and experiments have indicated that IL-22-IL-22R1-IL-10R2 binding can regulate IL-6, IL-17, IL-1β, TNF-α, and IFN-γ expression." (PMID 29358851, 2017). "The results of the present study demonstrated that anti-IL-22 nAb exerts a protective effect against the progression of cardiac hypertrophy induced by angiotensin II by upregulating the expression of inflammatory mediators, but this study has several limitations." (PMID 29358851, 2017). "We found that longer angiotensin II infusion resulted in higher levels of hypertrophy marker proteins, which represents a more serious degree of cardiac hypertrophy, with a parallel trend between the progressive increase in IL-22/IL-22R1 protein levels and the seriousness of cardiac hypertrophy." (PMID 29358851, 2017). "The downregulation of IL-22 may be a novel therapeutic strategy to prevent cardiac hypertrophy." (PMID 29358851, 2017). "Therefore, the increased IL-22/IL-22R1 protein levels in angiotensin II-induced hypertrophic hearts suggested that IL-22 may participate in myocardial hypertrophy." (PMID 29358851, 2017). "In the recent study, we investigate whether IL-22 is involved in cardiac hypertrophy." (PMID 29358851, 2017). "Therefore, this study aimed to investigate the role of IL-22 in cardiac hypertrophy mice." (PMID 29358851, 2017). "Treatment with mouse anti-IL-22 nAb resulted in a reduction in the HW/BW and LW/TL ratios and the CSA in angiotensin II-induced cardiac hypertrophy mice." (PMID 29358851, 2017). "Although clinical data have demonstrated that compared to the control group, higher serum IL-22 levels were observed in CHF patients with an NYHA class of II and III, the involvement of IL-22 in cardiac hypertrophy is still unknown, and the pathogenesis remains to be clarified." (PMID 29358851, 2017).
immune thrombocytopenia (2 papers, 2015 to 2021). "IL-22 plays an important role in the pathogenesis of immune thrombocytopenia." (PMID 26504852, 2015). "However, the effects of mesenchymal stem cells on IL-22 production in patients with immune thrombocytopenia remain unclear." (PMID 26504852, 2015).
Iron deficiency (2 papers, 2022). "Mice deficient in IL-22 have decreased transcriptional levels of the hepatic hepcidin 1 and pro-hepcidin gene in response to LPS, while treatment with the IL-22-Fc fusion protein leads to increased levels of hepcidin and iron deficiency in vivo." (PMID 35432360, 2022). "Iron deficiency may also result in chronic inflammation as an effect of the action of proinflammatory cytokines (IL-6, IL1β, and IL-22), and finally increase hepcidin expression." (PMID 35160288, 2022).
irritable bowel syndrome (2 papers, 2022 to 2025). Irritable bowel syndrome (IBS) is a chronic functional condition of the lower gastrointestinal (GI) tract characterized by abdominal pain or discomfort and disordered bowel habit (diarrhea, constipation, or fluctuation between the two). "The AhR/IL-22 pathway is anticipated to be a new target for addressing symptoms linked to post-infectious irritable bowel syndrome." (PMID 41019044, 2025).
Klebsiella pneumonia (2 papers, 2021). An pneumonia caused by infection with Klebsiella. "The rat β-defensin-2 and IL-22 emerged as biomarkers for the multidrug-resistant Klebsiella pneumoniae bacterial infection." (PMID 34671659, 2021). "IL-22 has an important role in the response to bacterial pathogens in several models of infectious diseases including Citrobacter rodentium colitis and Klebsiella pneumonia as well as Mycobacterium tuberculosis infections of the lungs." (PMID 33692792, 2021).
latent infection (2 papers, 2011 to 2022). "We confirm and extend our previous observations from latent M. tuberculosis infection, demonstrating that distinct, M. tuberculosis–specific IL-22–producing CD4+ T cells contribute a substantial portion to the total CD4+ T cell response to M. tuberculosis in both latent infection and TB disease." (PMID 35777848, 2022). "However, in 293T-BAC36 cells, in which BAC36 virions have established stable latent infection, it took 30 min of IL-22 treatment for a similar level of STAT3 and ERK 1/2 phosphorylation to occur." (PMID 21544244, 2011).
leishmaniasis (2 papers, 2015 to 2024). Infectious disease that is transmitted through the bite of hematophagous female phlebotomine sand flies. "However, IL-22 was found to be associated with control of inflammation and wound healing, but in a leishmaniasis model, this appears to be dependent on the level of tissue damage." (PMID 39844838, 2024). "Rather, Il22-/- mice exhibited more tissue damage than wild-type mice when infected with L. major or L. braziliensis, suggesting that IL-22 limits pathology when a threshold of inflammation is reached during leishmaniasis." (PMID 26285207, 2015). "Thus, one way IL-22 may enhance wound healing in leishmaniasis is by regulating L. major induced keratinocyte death." (PMID 26285207, 2015).
lupus erythematosus (2 papers, 2022 to 2025). An autoimmune, connective tissue chronic inflammatory disorder affecting the skin, joints, kidneys, lungs, heart, and the peripheral blood cells. "The frequencies of Th22 cells vary among different lupus erythematosus subtypes, indicating a prognostic role of IL-22 in various types." (PMID 35911703, 2022).
MALT lymphoma (2 papers, 2018 to 2019). An indolent, extranodal type of non-Hodgkin lymphoma composed of small B-lymphocytes (centrocyte-like cells). "Interestingly, single nucleotide polymorphisms in the IL22 gene increases the risk for the development of MALT lymphoma threefold, but how these genotypes influence IL-22 expression and function is not known." (PMID 29967613, 2018). "These hypotheses are supported by our findings that the IL-22 expression significantly correlated with the HP-dependent status of gastric MALT lymphoma." (PMID 30999581, 2019).
mucosal (2 papers, 2016 to 2021). "For example, chemotherapy drug methotrexate can induce acute mucositis featured by damage in the epithelium of small intestines, in which IL-22 plays an important restorative role in this self-resolving condition." (PMID 34992594, 2021). "These increases could result from the migration of IL-22-secreting T cells to sites of skin/mucosal inflammation." (PMID 27286889, 2016).
mycobacterial infection (2 papers, 2018 to 2023). "Although the impact of IL-17A and IL-22 on the immune response to MAC infection is not clearly understood yet, in a murine model, both IL-17A and IL-22 were shown to contribute to granuloma formation by M. tuberculosis, which appears to have a protective function during mycobacterial infection." (PMID 29401501, 2018).
mycosis fungoides (2 papers, 2020 to 2023). Classical mycosis fungoides is the most common type of mycosis fungoides (MF), a form of cutaneous T-cell lymphoma, and is characterized by slow progression from patches to more infiltrated plaques and eventually to tumors. "Our group reported that lesional skin of mycosis fungoides (MF) and Sezary syndrome (SS), representative diseases of CTCL, contained a high amount of IL-17 and IL-22, the latter of which was dominant." (PMID 32075269, 2020).
necrotizing enterocolitis (2 papers, 2019 to 2022). Necrotizing enterocolitis (NEC) is a devastating disease that affects mostly the intestine of premature infants. "Here we show that necrotizing enterocolitis in neonate mice is accompanied by elevation of IL-23 and IL-22 and decreased production of pancreatic enzymes." (PMID 31586069, 2019).
oral lichen planus (2 papers, 2020 to 2022). Oral lichen planus is a chronic inflammatory oral condition of unknown aetiology characterized by T-cell-mediated chronic immune response and abnormal epithelial keratinization cycle. "Furthermore, IL-22 and IL-23 levels were also shown to be significantly higher in patients with oral lichen planus, another chronic oral inflammatory disease." (PMID 35310855, 2022). "Increased IL-22 serum levels in patients with oral lichen planus may play an important role in the pathogenesis of oral lichen planus.The administration of the recombinant or antagonist of IL-22 could be a new therapeutic opportunity in the treatment of oral lichen planus." (PMID 33344684, 2020).
osteosarcoma (2 papers, 2022 to 2025). A usually aggressive malignant bone-forming mesenchymal neoplasm, predominantly affecting adolescents and young adults. "Furthermore, IL-22 accelerates the proliferation and invasion of osteosarcoma cells by activating STAT3." (PMID 35669104, 2022).
Parkinson disease (2 papers, 2021 to 2022). A progressive degenerative disorder of the central nervous system characterized by loss of dopamine producing neurons in the substantia nigra and the presence of Lewy bodies in the substantia nigra and locus coeruleus. "For this reason, experiments using animal models to examine the roles of IL-22 and IL-22Rα in the development and progression of Alzheimer’s and Parkinson’s diseases are warranted." (PMID 35054942, 2022). "From the list of proteins taking part in inflammation, IL-21, IL-22, IL-1B are important proteins that are involved in MS, Parkinson’s disease, and other viral-bacterial CNS infections." (PMID 33833673, 2021).
Peri-Implantitis (2 papers, 2014 to 2022). An inflammatory process with loss of supporting bone in the tissues surrounding functioning DENTAL IMPLANTS. "The present case-control study evaluated the gene expression of AhR, IL-22, and IL-6 in the peri-implant tissues of healthy and peri-implantitis patients." (PMID 35742682, 2022). "The aim of the present case control study was to investigate the levels of gene expression of Ahr, IL-22, and IL-6 in the peri-implant soft tissues of peri-implantitis and healthy patients." (PMID 35742682, 2022). "A case–control study indicated that there was an increased expression level of IL-22 and IL-23 in patients with peri-implantitis (P< 0.05)." (PMID 25297677, 2014). "The analysis of IL-22 expression levels for the healthy and peri-implantitis groups did not reveal significant differences between groups (p = 0.46)." (PMID 35742682, 2022).
pneumococcal pneumonia (2 papers, 2018 to 2023). A febrile disease caused by STREPTOCOCCUS PNEUMONIAE. "According to previous studies, IL-22 expression was rapidly upregulated in the lungs of mice suffering from pneumococcal pneumonia." (PMID 36839448, 2023). "Since surfactants have been shown to be important in restricting pneumococcal pneumonia, it is likely that the compounded effects of both surfactant and IL-22 depletion by PIV are aiding in pneumococcal ability to overcome mucosal barriers to invasive disease." (PMID 29720526, 2018). "The major cellular sources of IL-22 during pneumococcal pneumonia are innate-like cells (ILCs) and thymocyte cells (T cells) expressing γδ T-cell receptors, which are stimulated by IL-23 secreted from activated dendritic cells and macrophages in the lung." (PMID 29720526, 2018). "Based on these prior studies, we hypothesize that depletion of IL-22 by PIV in the localized lung environment exacerbates pneumococcal pneumonia and permits invasive disease mediated by Ply." (PMID 29720526, 2018). "PIV depletes IL-22 levels in vivo during active pneumococcal pneumonia." (PMID 29720526, 2018). "Consequently, IL-22 and IL-22BP coregulate antimicrobial immunity against S. pneumoniae, suggesting that IL-22RA2 may be an effective target for the treatment of pneumococcal pneumonia." (PMID 36839448, 2023). "IL-22 is required for host control of pneumococcal pneumonia, and IL-22 is cleaved by Pseudomonas PIV but not LasB." (PMID 29720526, 2018).
proliferative diabetic retinopathy (2 papers, 2012 to 2017). Advanced retinopathy due to diabetes mellitus characterized by the formation of new vessels in the retina. "The IL-22 level of PBMCs was significantly elevated in patients with proliferative diabetic retinopathy compared with the level in patients with non-proliferative diabetic retinopathy, patients with non-DR, and healthy controls." (PMID 22312190, 2012).
Respiratory tract infection (2 papers, 2018 to 2021). An infection of the upper or lower respiratory tract. "The subsequent sections highlight our current knowledge of the protective function of IL-22 during respiratory tract infections, including TB." (PMID 30319650, 2018). "However, recent studies suggest that Mtb induces expression of the IL-22R1 on infected macrophages and multiple studies have indicated a protective role of IL-22 in respiratory tract infections." (PMID 30319650, 2018).
retinal vasculitis (2 papers, 2013 to 2019). Inflammation of the retinal vasculature with various causes including infectious disease; lupus erythematosus, systemic; multiple sclerosis; behcet syndrome; and chorioretinitis. "In BD patients, a high IL-22 level in the supernatant of stimulated PBMCs correlated with the presence of retinal vasculitis and erythema nodosum." (PMID 23527071, 2013). "We showed that high IL-22 expression by activated PBMCs from BD patients correlated with the presence of retinal vasculitis, and erythema nodosum which similarly had noted lymphocytic vasculitis change in histopathology." (PMID 23527071, 2013). "The results showed that parameters such as “proportion of cells in the anterior chamber”, retinal vasculitis and erythema nodosum were significantly greater in the ‘high IL-22’ group than in the ‘normal IL-22’ group (p = 0.044, p = 0.005, p = 0.019 respectively)." (PMID 23527071, 2013).
scleritis (2 papers, 2019 to 2024). Inflammation of the sclera. "Additionally, elevated levels of IL-22 were detected in patients with scleritis and episcleritis." (PMID 38247834, 2024).
scleroderma (2 papers, 2018 to 2023). Scleroderma is a rare autoimmune connective tissue disorder characterized by abnormal hardening of the skin and, sometimes, other organs. "Expression of IL-22 in scleroderma skin is linked to both the inflammatory and fibrotic responses that are responsible for disease progression." (PMID 37753072, 2023). "In recent years, relationships between IL-22 and the pathology of various autoimmune diseases, such as Bechet's disease, psoriasis, scleroderma, and polymyositis, have been suggested, although details of their association remain unclear." (PMID 30619268, 2018).
skin abscess (2 papers, 2016 to 2018). "In a murine skin abscess model, the inhibition of either IL-17A or IL-22 alone resulted in significantly larger lesion size, indicating that both IL-17A and IL-22 are necessary for local control of SSTIs." (PMID 26901227, 2016). "To evaluate the role of Th1 or Th17 immunity against skin abscesses, we infected naive mice with S. aureus inocula that were premixed with recombinant mouse IFN-γ, IL-17A, IL-22, or a combination of different cytokines." (PMID 30327437, 2018).
Splenomegaly (2 papers, 2017 to 2021). Abnormal increased size of the spleen. "Meanwhile, we found that IL-22 KO or IL-22R KO MRL/lpr mice had milder lymphadenopathy and splenomegaly, which suggesting IL-22 or IL-22R deficiency may also reduce systemic immune response." (PMID 33717066, 2021).
squamous cell carcinoma of skin (2 papers, 2018 to 2020). "One study reports, an increased infiltration of cells secreting IL-22 specifically Th22 cells in squamous cells carcinoma of skin." (PMID 33042126, 2020). "IL-22 increased the proliferative as well as migratory potential of both basal cell carcinoma as well as squamous cell carcinoma of skin through STAT3 pathway and AKT." (PMID 33042126, 2020).